OR2W5 (olfactory receptor family 2 subfamily W member 5 (gene/pseudogene))
Description:
Odorant receptor.
Synonyms: OST722; formerly OR2W5P
Gene: Transcribed unprocessed pseudogene on chromosome 1 (247,491,128 to 247,492,090, forward strand). Ensembl gene ENSG00000203664.
Subcellular location: Cell membrane